IL6 (interleukin 6)
Diseases named in the same sentence as IL6 in open-access papers (continued):
Sharing a sentence is not in itself a finding about the gene and the disease.
coronary artery disease (continued). "Greater sensitivity and specificity than hs-CRP in predicting plaque instability were demonstrated by higher IL-6 plasma levels, which were also associated with thin-cap fibroatheroma in patients with ischemic heart disease as seen by optical coherence tomography." (PMID 40218291, 2025). "Similarly, Mendelian randomization studies have causally linked IL‐6 signaling to coronary heart disease." (PMID 40619914, 2025). "Similar to IL6R, we found that genetically downregulated IL-6 signaling via IL6 perturbation is associated with lower lifetime risks of coronary artery disease, peripheral artery disease and ischemic atherosclerotic stroke in individuals of European and East Asian ancestry." (PMID 40858837, 2025). "Since serum IL‐6 levels are largely determined by the genetic variant in IL‐6, this study was conducted to investigate whether the IL‐6 variant impacts cardiometabolic profile and the risk of premature coronary artery disease (PCAD)." (PMID 38634217, 2024). "Meta‐analysis of the IL‐6 rs1800795 variant with premature coronary artery disease." (PMID 38634217, 2024). "Sleep restriction in adult males who sleep normally leads to increased sympathetic, norepinephrine, and pro-inflammatory cytokines (interleukin-1, interleukin-6, and C-reactive protein) activity, which are independently associated with coronary heart disease and death." (PMID 37082612, 2023). "Additionally, studies have also indicated a rise in the levels of pro-inflammatory cytokines such as IL-6, which is associated with coronary artery diseases and vascular injury, thus contributing to accentuated CKD progression and mortality in this population." (PMID 37238983, 2023). "In addition, other data linked the blood serum levels of IL‐6 with upcoming cardiovascular events in patients with coronary artery disease." (PMID 35309153, 2022). "The importance of the pathology has been addressed where it has been reported that, in the absence of CPB, cardiac ischemia of hearts with coronary disease triggers increase in plasma IL-6 levels and the degree of IL-6 release is linked to the intensity of the coronary disease." (PMID 35935655, 2022). "Also, another link in the pathogenetic chain induced by IL6 that underlies the occurrence of ischemic heart disease is represented by the increase of blood viscosity, with the activation and proliferation of platelets." (PMID 34683106, 2021). "In individuals with ischemic heart disease, IL-6 plasma levels were associated with the presence of thin-cap fibroatheroma observed with optical coherence tomography, and IL-6 levels showed higher sensitivity and specificity than hs-CRP for the prediction of plaque instability." (PMID 33917744, 2021). "Reportedly, elevated IL-6 level is a risk factor for coronary heart disease (CHD)." (PMID 34123873, 2021). "On the other hand, the results suggest that a significantly increased IL-6 level is a predictor of multivascular coronary disease, which confirms the literature data, namely that a high IL-6 level is associated with a poorer prognosis, a higher risk of infarction and higher cardiovascular mortality." (PMID 34683106, 2021). "The cytokine, which was most strongly associated with the risk of coronary heart disease, was IL-6." (PMID 32775466, 2020). "More recently, in a collaborative meta-analysis, the presence of a minor genetic variant that impairs IL-6 signaling was associated with a reduction of coronary artery disease, indicating the presence of a causal association between IL-6 receptor-related pathways and coronary artery disease." (PMID 32485823, 2020). "Clinical studies have shown that serum IL-6 is elevated in coronary artery calcification in patients with chronic kidney disease and might be a predictive biomarker of mortality risk, coronary artery disease, and inflammation related to CVD." (PMID 31616435, 2019).
coronary artery disease (continued). "Furthermore, mendelian randomization studies of the IL-6R provided evidence for a causal mechanism of IL-6 signaling in the development of coronary artery disease." (PMID 30367209, 2019). "In that study, the plasma level of lutein was inversely associated with IL-6 in serum from patients with coronary artery disease and lutein did also attenuate the release of inflammatory cytokines by lipopolysaccharide-treated peripheral blood mononuclear cells ex vivo." (PMID 29696082, 2018). "Additionally, the C allele of IL-6 -592A>C (OR=1.65, 95%CI=1.29-2.11) was correlated with a higher risk of developing coronary artery disease in comparison to the A allele." (PMID 27648032, 2016). "Additionally, the C allele of IL-6 -592A>C (OR=1.65, 95%CI=1.29-2.11) was correlated with an elevated risk of developing coronary artery disease in comparison to the A allele." (PMID 27648032, 2016). "Using unconditional regression analysis, we observed that the AC and CC genotypes of IL-6 -592A>C were associated with the increased risk of developing coronary artery disease when compared with the AA genotype, and the adjusted ORs (95%CI) were 1.63(1.12-2.38) and 2.70(1.57-4.67), respectively." (PMID 27648032, 2016). "In addition to its function as a stimulator of CRP synthesis, IL-6 has been shown to correlate with an increased risk of coronary heart disease in prospective studies." (PMID 26378571, 2015). "Long-term circulating IL-6 levels may be associated with coronary heart disease, such as the main risk factors already established." (PMID 26100072, 2015). "Long-term circulating interleukin 6 levels in prospectively collected blood are predictive of subsequent risk of coronary heart disease, making IL6 a strong candidate gene for modifying air pollution effects on coronary heart disease related phenotypes including mortality." (PMID 25133672, 2014). "Low-grade chronic inflammation is now widely thought to play an important role in the process of atherogenesis, and levels of inflammatory markers such as C-reactive protein (CRP), interleukin (IL)-6, and fibrinogen are moderately associated with risk of coronary heart disease (CHD) events." (PMID 19554082, 2009). "Therefore, we hypothesized that the function of EPCs in patients with unstable angina pectoris is related to the degree of coronary artery disease, which may be caused by the increase in IL-6." (PMID 35847417, 2022). "Therefore, other consequences of reduced interleukin-6 signalling could be responsible for the association with decreased risk of coronary heart disease that we identified." (PMID 22421340, 2012). "Independently of high cholesterol or myocardial damage markers, IL-6 predicts future adverse cardiovascular events and reflects increased inflammatory activity in plaques and is therefore a strong marker of increased risk for mortality in coronary artery diseases." (PMID 19240794, 2009). "For instance, a MR study investigating the link between interleukin 6 and coronary artery disease found an odds ratio of 0.64 (95% confidence interval 0.54 to 0.76)." (PMID 40547872, 2025). "In the cardiovascular system, the cytokine IL-6 plays a crucial role in ischemic heart diseases and its complications by promoting atherosclerotic plaque destabilization." (PMID 40048077, 2025). "Individuals with elevated hsCRP and SAA or IL-6 showed higher prevalence rates of coronary artery disease, heart failure, and adverse metabolic traits." (PMID 40806466, 2025). "Research indicates that an increase in DII scores correlates with elevated levels of interleukin-6 (IL-6), tumor necrosis factor-alpha (TNF-α), and C-reactive protein (CRP), as well as an increased risk of coronary heart disease development." (PMID 39796599, 2025). "Elevated IL-6 levels predict cardiovascular events in both unstable and stable coronary disease, underscoring its utility as a biomarker for adverse cardiovascular outcomes." (PMID 40244022, 2025).
coronary artery disease (continued). "Extensive literature suggests that the IL-6 trans-signaling pathway plays a pivotal role in the IL-6 signaling cascade within coronary artery disease." (PMID 39229261, 2024). "Advanced age, coronary artery disease, and elevated levels of interleukin-6, procalcitonin, D-dimer, and sCr were considered potential risk factors for myocardial injury among elderly patients infected with the Omicron variant." (PMID 38420262, 2024). "Unstable coronary disease patients with complicated hospital courses had higher IL-6 levels than patients with uneventful courses." (PMID 38256155, 2024). "Reports have found that IL-6 is involved in the pathogenesis of coronary heart disease and is closely related to the severity of coronary artery disease with a higher level of IL-6 related to severe conditions of patients with coronary heart disease." (PMID 38935941, 2024). "In predicting coronary artery disease, the mean AUC for IL-6 and CRP were 0.74 (95% CI: 0.57-0.84) and 0.60 (95% CI: 0.44-0.74), respectively." (PMID 39280000, 2024). "Our findings align with a previous study that examined the effects of a daily 300mg aspirin dosage on hs-CRP and IL-6 levels in 40 men with coronary artery disease." (PMID 38899239, 2024). "Coronary artery disease patients who were given an aerobic exercise program in rehabilitation showed reduced circulating levels of pro-inflammatory cytokines, including IL-6." (PMID 38256155, 2024). "IL-6 has a certain predictive valuefor the progression of NTLs and provides guidance for secondary prevention in themanagement of coronary heart disease." (PMID 39139413, 2024). "The correlation between the increase of CRP and IL-6 and the formation of unstable atherosclerotic plaques and the correlation between coronary artery disease and SCD has been established." (PMID 38507154, 2024). "Advanced age, coronary artery disease, interleukin-6 > 22.69 pg/ml, procalcitonin > 0.0435 ng/ml, D-dimer > 0.615 mg/L, and sCr > 81.30 μmol/L are potential risk factors of myocardial injury." (PMID 38420262, 2024). "IL-6 levels were also higher in patients with ischemic heart failure compared to simple coronary artery disease." (PMID 38256155, 2024). "Previous studies have shown a similar association of IL-6 levels in elderly patients with established CVD, a patient cohort with known risk factors for a pro-inflammatory state (aging, coronary artery disease, etc)." (PMID 39077632, 2024). "These included advanced age, pre-existing coronary heart disease, interleukin-6 levels >22.69 pg/ml, procalcitonin levels >0.0435 ng/ml, D-dimer levels >0.615 mg/L, and sCr levels >81.30 μmol/L." (PMID 38420262, 2024). "Elevated IL-6 levels are strongly correlated with future cardiac events and mortality in populations with stable coronary artery disease (CAD) during long-term observation." (PMID 39408157, 2024). "The insights of Alter and colleagues underscore the complexity of IL-6 biology in ischemic heart disease." (PMID 37259918, 2023). "IL-6 is a pleiotropic pro-inflammatory cytokine which is found at high levels in human atherosclerotic plaques and in the blood of patients with coronary artery disease." (PMID 37049512, 2023). "Particularly, patients with family history of premature coronary artery disease have a significantly higher level of plasma IL-6." (PMID 40589521, 2023). "The findings underscore the complexity of IL-6 biology in ischemic heart disease and identify an adenosine/IL-6 pathway that warrants consideration for targeting as a modulator of cardiovascular risk." (PMID 37259918, 2023). "Several proinflammatory cytokines, such as IL-6, IL-18, TNF-α and C-reactive protein, have been reported to be independently associated with the risk of coronary heart disease." (PMID 37308900, 2023). "Clinical data support important roles of IL-6 and oxLDL in atherosclerosis and coronary artery disease." (PMID 40589521, 2023).
coronary artery disease (continued). "According to the literature, IL-6 is a biomarker of inflammation used to evaluate the severity and prognosis of coronary heart disease." (PMID 37175097, 2023). "Among others, extensive IL-6 secretion can trigger coagulation and vascular leak syndrome leading to cardiomyopathy, coronary artery disease and myocardial dysfunction." (PMID 35860660, 2022). "In this regard, it has been shown that administration of L-carnitine at a dose of 1000 mg/d for 12 weeks in cases with coronary artery disease causes a significant reduction in the level of inflammatory biomarkers such as TNF-α and IL-6." (PMID 35936217, 2022). "In patients with coronary artery disease, treatment with Aronia for 6 weeks reduced IL-6 and Monocyte chemoattractant protein-1 (MCP-1) concentrations." (PMID 35831939, 2022). "In coronary artery disease, losartan was shown to decrease IL-6 level, and increase both TGF-β and IL-22 levels." (PMID 35163696, 2022). "Coronary heart disease and heart failure significantly increase the production of potent inflammatory cytokines (interleukin-1—IL-1; interleukin-6—IL-6; tumor necrosis factor-α—TNF-α) in the heart and other organs." (PMID 36430892, 2022). "AAA patients have significantly higher levels of serum IL-6 than either coronary heart disease patients or control subjects." (PMID 35685724, 2022). "There were a higher proportion of patients with more severe coronary disease, including two-vessel and multivessel disease, in the higher IL-6 group." (PMID 36028849, 2022). "Previous studies have indicated the role of TNF-α and IL-6 in cardiac remodeling, fibrosis, cardiomyocyte apoptosis and ischemic heart disease." (PMID 34046187, 2021). "IL-6 signaling is in connection with atheromatous plaque formation and instability, and plasma IL-6 levels are used as a marker for cardiovascular diseases such as coronary artery disease and AS." (PMID 34504432, 2021). "Clinical trials using tocilizumab, a monoclonal antibody that neutralizes IL-6, show lower inflammation in individuals with acute coronary syndromes, compatible with a beneficial effect of overall IL-6 inhibition in patients with coronary artery disease." (PMID 33924019, 2021). "Captopril used in coronary artery disease and ischemic heart diseases reduced inflammation in vivo by lowering the level of IL-6, and increasing the level of TGFβ since the macrophages are in vivo activated with drugs." (PMID 34768805, 2021). "In myocarditis, coronary heart disease and other chronic immune diseases, the level of IL-6 is significantly elevated and related to disease severity." (PMID 33171330, 2021). "IL-6 is a multifunctional cytokine that plays an important role in the development of ischemic heart diseases." (PMID 34576113, 2021). "This study showed a relationship between IL-6174G> C and Interleukin-6 (IL-6) 572 C>G genes and coronary artery disease." (PMID 33436103, 2021). "Circulating IL-6 levels and at least one polymorphic form of IL6 gene (IL6 -174 G/C, rs1800795) have been shown to be independently associated with coronary artery disease (CAD) by several investigators." (PMID 34595552, 2021). "A similar reduction in basal IL-6 was found in obese individuals subjected to a hypocaloric diet and regular aerobic exercise and in patients with coronary artery disease after training." (PMID 34707507, 2021). "On the other hand, serum IL-6 levels are high in people with unstable angina, which is a symptom of coronary artery disease." (PMID 33436103, 2021). "Literature studies have confirmed the interrelation between high IL-6 levels and coronary disease, as well as the role of IL-6 assessment for the early detection of patients with extensive coronary lesions." (PMID 34683106, 2021). "The serum profiling reveals elevated values of IL-17A, IL-6, C-X-C motif chemokine ligand 10 (CXCL10) and higher values of markers associated with coronary artery disease." (PMID 33921718, 2021).
coronary artery disease (continued). "Higher levels of interleukins (IL-6, -18) and tumor necrosis factor alpha (TNF-α) were also associated with development of coronary artery disease (CAD), cerebrovascular diseases and ACS, but their exact role is yet to be determined in larger clinical trials." (PMID 34207266, 2021). "Interleukin-6 (IL-6) is essential to inflammatory processes correlated with chronic inflammatory diseases, such as coronary heart disease (CHD)." (PMID 34884952, 2021). "It was previously reported that IL6 circulatory levels, in patients with coronary heart disease, are correlated to PMP and EMP levels." (PMID 33193304, 2020). "Regarding the role of the circulating level of IL-6 in predicting future coronary heart disease events, a decrease in IL-6 level following olive oil consumption can reduce the risk of cardiovascular events." (PMID 32795310, 2020). "Nuclear translocation of dimeric PKM2 boosts the transcription of IL-1β and IL-6 in LPS-activated macrophages from patients with coronary artery disease." (PMID 32938830, 2020). "TC and LDL-C levels are important for risk evaluation of coronary heart disease, which benefits from statin therapy through the reduction in LDL-C, hs-CRP, and IL-6 levels." (PMID 32652935, 2020). "High levels of IL-6 and CRP were significantly associated with an increased risk of coronary disease in both sexes, while high levels of soluble TNF receptors were significantly associated only among women." (PMID 31337127, 2019). "IL-6 seems strongly involved in the coronary heart disease (CHD), especially via the trans-signaling pathway." (PMID 31369575, 2019). "Key implications of IL6 in cancer, inflammation, coronary artery disease (IL6R), hematopoiesis, and metabolic processes have been reported." (PMID 31658298, 2019). "The differences in serum CP-IgA, hs-CRP and IL-6 levels between patients with different severities of coronary artery disease and subjects in the control group were statistically significant (P = 0.000)." (PMID 31088358, 2019). "Previous studies also have revealed that elevated plasma concentrations of adhesion molecules are related to IL-6 in patients with various diseases, including carotid atherosclerosis, coronary artery disease, and migraine." (PMID 30400334, 2018). "By measuring IL-6 levels in blood samples of coronary heart disease patients, it was found that blood IL-6 levels were higher in the coronary heart disease group than in healthy subjects." (PMID 30142970, 2018). "Of interest, STAT3 is required for Flt3-dependent formation of DCs from bone marrow derived cells, and plays an important role in production of IL-1β, IL-6, and TNFα in macrophages of humans with coronary artery disease." (PMID 29800237, 2018). "In some studies, EMPs level is correlated with serum IL-6 level, in both healthy subjects and in patients with coronary heart disease." (PMID 28049487, 2017). "This investigation is a subanalysis of the article entitled “The Interleukin 6 c.-174 CC genotype is a predictor for new cardiovascular events in patients with coronary heart disease within three years follow-up“ (ClinicalTrials.gov identifier: NCT01045070)." (PMID 27570807, 2016). "IL6R encodes the receptor for the pro-inflammatory cytokine interleukin-6 and circulating levels of a soluble form of IL6R have been associated with coronary artery disease." (PMID 25835000, 2015). "For example, in patients with stable coronary artery disease, circulating C-reactive protein, and IL-6 levels were significantly reduced after regular EXE by 41 and 18%, respectively." (PMID 26600018, 2015). "For instance, human population studies have associated interleukin-6, C-reactive protein and TNF-α to age-related chronic diseases, like coronary heart disease and disability." (PMID 25888078, 2015). "Along the same line, a reduction in systemic IL-1, IL-6 and increased in IL-10 levels was reported in coronary heart disease patients in response to a 12-week aerobic EXE training program." (PMID 26600018, 2015).